IL10 (interleukin 10)
Diseases named in the same sentence as IL10 in open-access papers (continued):
Sharing a sentence is not in itself a finding about the gene and the disease.
Autoimmunity (continued). "This has been shown to occur in other models of autoimmunity in an IL-10 dependent manner." (PMID 19142233, 2009). "The DDIT4-dependent regulatory cascade may also exert beneficial effects in diabetic wound healing by abolishing macrophage proinflammatory activation, and, apart from autocrine signaling, IL-10 can be delivered by other cells, including regulatory B lymphocytes, to prevent autoimmunity." (PMID 40806725, 2025). "Regulatory T cells (Tregs): Tregs are essential for the prevention of autoimmunity and have a suppressive effect on effector T cells.MDSCs: MDSCs inhibit specific and nonspecific T-cell responses by producing large amounts of nitric oxide, arginase-1, and immunosuppressive cytokines, such as IL-10." (PMID 40672947, 2025). "In addition to encouraging naïve T cells to differentiate into regulatory T cells (Tregs), which are necessary for immunological tolerance maintenance and autoimmunity prevention, IL-10 also improves myeloid cells' capacity to take on an anti-inflammatory phenotype." (PMID 39806495, 2025). "Alternatively, it is possible that CMV-induced immunoregulatory pathways, including interleukin-10 (IL-10) secretion, may dampen local inflammation in areas of CMV reactivation, thereby reducing the risk of autoimmunity responsible for the neurological symptoms of LC." (PMID 39685583, 2024). "To explore the differences in IL-10 producing PB-PCs from mice with active lupus that could render these cells unable to suppress autoimmunity effectively, we sought to establish a baseline of gene signatures expressed by Bregs from the PB-PC lineage in a normal immune response." (PMID 38155972, 2023). "Interestingly, we noticed an increase in the IL-10 level in the cord blood of PE through cytokine array analysis, while IL-10 has been demonstrated as a key anti-inflammatory mediator to regulate wound healing, autoimmunity, cancer, and homeostasis." (PMID 38203391, 2023). "Finally, although no mouse model duplicates all features of postinfectious LA, mouse models, such as the IL-10–knockout mouse (Il-10–/–), may be valuable in further exploration of the infection-induced autoimmunity hypothesis proposed here." (PMID 37471146, 2023). "However, the functional role of rs1800896 on IL10 expression and IL-10 secretion could be different in the context of Gram-positive bacterial infection, anti-tumor immune response, or autoimmune disorders." (PMID 36233253, 2022). "Cells within the CD4_Stim2.Th17.1 cluster expressed genes associated with regulatory function (IL10, ITGA2), whereas cells within the CD4_Stim2.Th17.2 cluster expressed proinflammatory effectors (IFNG, IL23R, PRF1), described to be produced by pathogenic Th17 cells in autoimmunity." (PMID 35192548, 2022). "This transition of an ”IFN-γ only into an IFN-γ—IL-10 co-expression Th1 state” might represent an important intrinsic self-regulatory mechanism of Th1 cells to shut down their effector functions, limiting overwhelming inflammation and autoimmunity." (PMID 33572870, 2021). "In this sense, the objective of the present study was to identify polymorphisms in important mediators of the immune response (FOXP3, IFNG, IL6, IL8, IL10, MBL2, CRP, TGFΒ1 and TNFA) in association with ANAs, which could contribute to the development of autoimmunity in hepatitis C." (PMID 32743104, 2020). "Taken together, there may not be a simple correlation between Tregs, Bregs, IL-10 and IgG4 autoantibodies, since IL-10 does have multiple function in immune regulation, and may have both anti- and pro-inflammatory effects, also in the context of IgG4-autoimmunity." (PMID 33584677, 2020). "Although mechanisms that mediate development and induction of the Bregs have thus far remained unclear, a study suggested that the increased IL-10+ Bregs may be secondary to expanded T follicular helper (Tfh) cells provide help to effector B cells and promote autoimmunity." (PMID 33198645, 2020).
Autoimmunity (continued). "CD8+CD122+ T cells contain an abundant subset of PD-1+ cells that are CD8+ Treg cells; these Treg cells (CD8+CD122+PD-1+) are capable of suppressing autoimmunity and alloimmunity mainly through their secretion of IL-10, and are largely CD127 (encoded by IL-7Rα) negative." (PMID 29780389, 2018). "Moreover, GAG regulates autoimmunity by increasing immunosuppressive cytokine IL-10." (PMID 28947964, 2017). "TIM-1 is an inclusive marker for IL-10+ Bregs and an important receptor for Breg induction and function in mice, probably by sensing of apoptotic cells and induction of IL-10 expression on B cells, in order to preserve tolerance to self-antigens and prevent autoimmunity." (PMID 28103916, 2017). "Thus, the resolution of autoimmunity in FasC194Vlpr/lpr mice is associated with decreased expansion of follicular and extrafollicular helper T cells, but not increased Treg numbers or IL-10 levels." (PMID 28008916, 2016). "Thus, in contrast to primary beneficial effects of IL-10 in autoimmune disorders, an ambivalent function of IL-10 has to be considered in infectious CNS diseases, contributing to insufficient protective (e.g. antiviral) immunity on the one hand, but limiting immunopathology on the other." (PMID 27611574, 2016). "However whether CD11b and its signaling can control autoimmunity via IL-10 production remains unclear." (PMID 27188220, 2016). "Thus, our data expanded the prevailing belief that Tfh cells only augment autoimmunity and demonstrated that Tfh cells may function to maintain immune homeostasis by expanding the regulatory B-cell pool and stimulating IL-10 production via induction of IL-21." (PMID 23638156, 2013). "These subpopulations are phenotypically distinct: Th17 cells that mediate autoimmunity are characterized by high levels of IL-23R, IL-33 and T-bet expression when compared to their non-pathogenic counterparts that express elevated levels of IL-10." (PMID 23844143, 2013). "Regulatory T cells (Tregs), which typically express FOXP3 and produce IL-10 and TGF-β, are generally responsible for suppressing autoimmunity." (PMID 41465549, 2025). "Bregs suppress excessive inflammation through IL-10 production and maintain immune homeostasis, thus preventing immune-mediated diseases such as IBD and other autoimmune conditions." (PMID 40564077, 2025). "Thus, DEGs from IL-10+ B cells in the context of active autoimmunity were indicative of response to a heightened inflammatory environment resulting in immune activation and exposure to intra- and extra-cellular stressors that could affect the ability of these cells to function as immune regulators." (PMID 38155972, 2023). "It has been reported that IL10 and TGF-β had anti-inflammatory properties and played a key role in disease prevention and autoimmunity." (PMID 36936973, 2023). "Tregs return to the gut where they induce immune tolerance directly as well as through the production of immunosuppressive cytokines such as interleukin 10 (IL-10), TGF-β (tumor growth factor) and IL-35 to prevent autoimmunity." (PMID 36428677, 2022). "IL-10-secreting T regulatory type 1 (Tr1) cells are an important subset of CD4+ T cells that control excessive inflammation and autoimmunity by inhibiting the functions of antigen-presenting cells and antigen-specific effector T cells." (PMID 36056390, 2022). "IL-10 and TGF-β1 are widely accepted as immunoregulatory cytokines with a critical role in restoring immune homeostasis and are hence tightly involved in autoimmune pathologies." (PMID 36233253, 2022). "Here the authors show that the function and homeostasis of mouse and human IL-10+ Breg cells are negatively regulated by the cell surface receptor, SLAMF5, to impact experimental autoimmunity, thereby hinting SLAMF5 as a potential target for immunotherapy." (PMID 33767202, 2021).
Autoimmunity (continued). "Although differences were observed amongst these tissues, either IL-10 or TGF-β was increased by LL-CFA/I, but one or both cytokines are often necessary to regulate inflammation and subdue autoimmunity." (PMID 33823920, 2021). "Studies from models of autoimmunity indicate that regulatory CD4+ T cells and IL-10 represent a fundamental mechanism for regulating IL-17A." (PMID 34772416, 2021). "These cells inhibit T cells through the release of IL-10, IL-35, and transforming growth factor β (TGF-β) and their importance is known for several autoimmune conditions." (PMID 34621271, 2021). "For example, red pulp macrophages can prevent autoimmunity by producing anti-inflammatory cytokines, such as TGF-β and IL-10, and by inducing T-regulatory cells." (PMID 29691378, 2018). "IL-4 promotes the differentiation of CD4 T cells toward the Th2 phenotype, and IL-10 and TGF-β are known to exert anti-inflammatory activity and to suppress autoimmunity through mechanisms that include the induction of Treg44." (PMID 28851867, 2017). "Antigen-specific IL-10-secreting CD4+ T cells (Tr1) and Foxp3+ regulatory T cells (Tregs), both known to control autoimmunity and induced following JHMV infection, were assessed for their relative in vivo suppressive function of SR T cells." (PMID 27708643, 2016). "MSCs can also secrete inhibitory cytokines, such as IL-10 and TGF-β1, which are potent inhibitors of T cell autoimmunity." (PMID 27905403, 2016). "We show that although suppression of autoimmunity and expansion of these cell subsets localize to different regions on NZB c4, both are dependent upon IL-10." (PMID 26964093, 2016). "In the MRL/lpr mice model, which have a defect in Fas and are therefore prone to autoimmunity, induction of regulatory B cells through anti-CD40 stimulation and subsequent adoptive transfer was shown to have an IL-10 dependent protective effect." (PMID 26964093, 2016). "RPMΦs can also prevent autoimmunity by producing anti-inflammatory cytokines such as TGF-β and IL-10 and by inducing generation of regulatory T (Treg) cells." (PMID 26441984, 2015). "IL-27 was shown to be a key regulator of IL-10 and IL-17 production by human CD4+ T cells thus providing a dual regulatory mechanism to control autoimmunity and tissue inflammation." (PMID 25698903, 2015). "RPMΦs can also prevent autoimmunity by producing anti-inflammatory cytokines such as TGF-β and IL-10 and by inducing the generation of Treg cells." (PMID 26441984, 2015). "Tregs secrete the anti-inflammatory cytokines IL-10 and TGF-β to suppress the immune response, maintain immunologic homeostasis, and prevent autoimmunity." (PMID 24991091, 2014). "IL-10 is well known to inhibit the synthesis of pro-inflammatory cytokines specifically TNF-alpha from monocytes and macrophages in autoimmunity." (PMID 25002862, 2014). "B cell negative regulation of immune responses through the production of IL-10 has been demonstrated in EAE and other mouse models of autoimmunity and inflammation." (PMID 21799861, 2011). "While suppressor T cells use IL-10 and TGF-β signaling to promote immunological tolerance, regulatory T cells (Tregs), which are identified by their expression of FOXP3, are essential in preventing autoimmunity." (PMID 39996755, 2025). "Candida species could activate dendritic cells or macrophages, leading to IL-6, IL-10, TNF-α and anti-dsDNA production, thus perpetuating autoimmunity." (PMID 39637140, 2024). "In contrast, IL-10 was found to be increased and IFN-γ was decreased in the skin lesions of multiparous lupus-prone mice highlighting the role of IL-10 as a suppressor on skin lupus by possibly suppressing T-lymphocyte driven autoimmunity." (PMID 35873599, 2022). "In addition to IL-10 regulation, compensatory mechanisms such as the CD24-Siglec G pathway can protect the host from apoptotic-debris-induced-autoimmunity by discriminating between DAMPS and PAMPS." (PMID 35615359, 2022).
Autoimmunity (continued). "Likewise, monitoring of beta-cell specific autoimmunity by proliferation and ELISPOT analyses suggest that circulating effector T cells reactive to proinsulin peptide disappeared or became suppressed by IL-10 producing autoantigen-specific Tregs." (PMID 36505460, 2022). "Herein, we report that depletion of Optn in mice by CD11c-Cre promotes JAK2-STAT3 phosphorylation and the forming of IL-10/JAK2/STAT3/IL-10 positive feedback loop, thus impairing DC maturation and the priming of CD4+ T cells to prevent the development of autoimmunity in mice." (PMID 34707127, 2021). "In the context of autoimmunity, TR1 cells might importantly contribute to immune tolerance, and in contrast to IL-10+ B-helper T cells, mediate disease control." (PMID 33572870, 2021). "Using cytokines like IL-10, CD5 positive cells have a role in the prevention of autoimmunity." (PMID 33585004, 2020). "Gene therapy with the anti-inflammatory cytokine interleukin-10 (IL-10) induces Tregs and prevents T1D in NOD mice, setting the stage for the development of other immunoregulatory therapies to prevent or reverse autoimmunity." (PMID 31466263, 2019). "The importance of IL-10 in mediating the suppressive effect of Bregs is well established, and its role is corroborated by in vivo results showing that mice lacking IL-10-producing B cells develop exacerbated autoimmunity." (PMID 31722204, 2019). "Similar to our analysis, also other studies with a control group did not confirm the presence of a relationship between the autoimmunity process and anti-inflammatory cytokine secretion (IL-10 and TGF-β)." (PMID 29915563, 2018). "To further address the in vivo relevance of Ch25h in inducing IL-27-driven TR1 cells and the potential effect on regulating autoimmunity and tissue inflammation, we conducted repeated in vivo treatments with anti-CD3 to induce IL-10+ regulatory T cells, that have been shown to be IL-27 dependent." (PMID 28993775, 2017). "The upregulation of IL-10 production in ECN-treated mice may be one of the mechanisms preventing inflammation and autoimmunity." (PMID 28959254, 2017). "In SLE, defects in IL-10 secretion permit pre-naïve B cells to promote CD4+ T-cell activation and may thereby enhance the development of autoimmunity." (PMID 26209442, 2015). "A link between reduced B-cell immunoregulatory function and age-related autoimmunity is supported by our data showing a negative correlation between CD19+CD24hiCD38hi B-cell IL10 production and serum Rf levels in our subjects." (PMID 23755918, 2013). "In experimental models of autoimmunity including EAE and EAM, IL-10 suppresses disease severity." (PMID 19587788, 2009). "On the other hand, mTORC1 has been proposed to mediate TNF-induced IL-10 expression and the STAT3-initiated cascade in synovial macrophages, whereas pharmacological blockage of Cot/Tpl-2/MAP3K8 in macrophages has been suggested to induce therapeutic effects in various autoimmune disorders." (PMID 40806725, 2025). "The lack of spontaneous inflammation or autoimmunity in Ikzf1-fl-Foxp3-Cre mice is similar to mice with Treg-specific deletion of Prdm1, Icos, Il10 and Mef2d." (PMID 38655862, 2024). "Additionally, Treg IL-10 production regulated the Th17 response in the TME, with TME-specific type I IFN signaling promoting Treg activation and IL-10 synthesis to counteract Th17 inflammation and prevent tumor development or autoimmunity." (PMID 38672681, 2024). "Moreover, vitamin D supplementation has shown promise in reducing antithyroid antibody levels, improving thyroid function, and improving other markers of autoimmunity, such as cytokines, e.g., IP10, TNF-α, and IL-10, and the ratio of T-cell subsets, such as Th17 and Tr1." (PMID 37513592, 2023).
Autoimmunity (continued). "Besides the induction of PD-L1 expression in tumor cells, IL-27 may have additional immune-suppressive activities through the induction of IL-10-producing or PD-L1-expressing regulatory-type CD4+ T cells, such as described in autoimmunity and GVHD models." (PMID 34439164, 2021). "Although we have shown that the model apitope 4Y induces regulatory Tr1 cells, we did not know whether these cells and other IL-10 producing regulatory populations would migrate from lymphoid tissues to control autoimmunity in other organs." (PMID 33936079, 2021). "In addition, Ginsenoside Rd displayed the therapeutic function to EAE specifically by modulating inflammation and autoimmunity, via the downregulation of related proinflammatory cytokines IL-6 and IL-17, upregulation of inhibitory cytokines TGF-β and IL-10, and regulation of Treg/Th17 imbalance." (PMID 33380901, 2020). "However, in another study, B-cell-specific IL-10 deletion did not affect lupus progression, implying that endogenous IL-10 producing Breg cells are ineffective in suppressing autoimmunity in MRL/lpr mice." (PMID 33240280, 2020). "It had been found that the IL-10 production was dramatically higher in RA, primary SjS, and SLE patients than in HCs that could play a role in B cell extreme activity and in the progression of autoimmunity." (PMID 28265257, 2017). "Abatacept did affect T cell activation systemically but, extrapolating from the data in autoimmune pathologies cited above, it may not affect T cell-independent innate immune responses, even if its action is dependent on IL-10." (PMID 28262700, 2017). "Our data suggests that IL-10 may act through multiple mechanisms to prevent the progression of autoimmunity and our work adds to this literature by highlighting the novel role it may play in supporting the expansions of suppressive populations." (PMID 26964093, 2016). "Moreover, the protective role of T regulatory cells and their cytokines IL-10 and TGF-β in systemic autoimmunity argues that the fibrotic process elicited by silica exposure may negatively regulate the development of autoimmunity." (PMID 27014276, 2016). "However, the relative contribution of IL-10 and IL-27 in suppressing Th17-mediated autoimmunity in vivo remains not clear." (PMID 27308096, 2016). "Induction of adaptive Treg (iTreg) and increased secretion of IL-10 and TGF-β have been reported in several studies that employed different antibody- or antibody fraction-based biologicals to prevent or control experimental autoimmunity, through not fully understood mechanisms." (PMID 26517875, 2015). "This might explain why systemic administration of immunosuppressive cytokines, like IL-10, have not always resulted in efficacious treatment of autoimmunity; local IL-10 increase would maintain survival and stability of a network of tDC : Treg:Breg:imprinted DC." (PMID 37388741, 2023). "In mouse models and in humans, T cells nonresponsive to IL-10 escape Treg control, proliferate to a greater degree, and produce higher amounts of inflammatory cytokines such as Th17 and IFNγ, both of which activate macrophages and promote cellular autoimmunity." (PMID 32303238, 2020). "Possible combination blockades of IL10 and Nrp-1 via bispecific antibodies or soluble antagonists may one day be a viable therapeutic strategy to limit tumor-induced tolerance without evoking autoimmunity." (PMID 27075020, 2016). "A balance between IL-10 and IFN-γ secreted by TH1 cells is thought to allow an effector response that is sufficiently strong but not excessive as in autoimmunity." (PMID 26475448, 2016). "EGR3 is a member of a zinc finger transcription factor that plays an important role in regulating immune responses inducing also the expression of anti-inflammatory cytokines such as IL-10 and TGFB124, however the role of EGR3 in autoimmunity it is not clear yet." (PMID 39013887, 2024).